KIFC2 (kinesin family member C2)
Description:
May play a role in microtubule-dependent retrograde axonal transport. May function as the motor for the transport of multivesicular body (MVB)-like organelles in dendrites (By similarity).
Tractability: PROTAC: its protein half-life has been measured.
Gene: Protein-coding gene on chromosome 8 (144,465,940 to 144,474,202, forward strand). Ensembl gene ENSG00000167702.
Subcellular location: Cytoplasm, cytoskeleton
Subcellular location (Human Protein Atlas): Nucleoplasm; Cytosol
Pathways (Reactome):
Hemostasis: Kinesins
Vesicle-mediated transport: COPI-dependent Golgi-to-ER retrograde traffic
Gene Ontology:
Molecular function: plus-end-directed microtubule motor activity; ATP binding; microtubule binding; microtubule motor activity
Biological process: anterograde dendritic transport of neurotransmitter receptor complex; axon guidance; synaptic vesicle transport; microtubule-based movement
Cellular component: kinesin complex; cytoskeleton; dendrite cytoplasm
Genetic constraint (gnomAD): Loss-of-function variants: 91 observed, 85.52 expected, observed/expected ratio (o/e) 1.06, 90% interval 0.9 to 1.27. The synonymous counts are far from expectation, so gnomAD's model fits this gene poorly and the ratio says little. Missense variants: 1,277 observed, 980.32 expected, observed/expected ratio (o/e) 1.3, 90% interval 1.24 to 1.36. Synonymous variants: 692 observed, 445.05 expected, observed/expected ratio (o/e) 1.55, 90% interval 1.46 to 1.66.
Homologues: Orthologues: macaque KIFC2 (98% identical), chimpanzee KIFC2 (91% identical), pig KIFC2 (85% identical), dog KIFC2 (84% identical), mouse Kifc2 (83% identical), rat Kifc2 (81% identical), guinea pig KIFC2 (79% identical), tropical clawed frog kifc2 (36% identical), zebrafish si:ch211-257p13.3 (34% identical), Caenorhabditis elegans klp-3 (23% identical). Paralogues in human: KIFC3 (30% identical), KIF13B (20% identical), KIF13A (19% identical), KIFC1 (19% identical), KIF16B (19% identical), KIF14 (19% identical), KIF26A (19% identical), KIF12 (18% identical), KIF19 (18% identical), KIF4B (18% identical), KIF4A (18% identical), KIF11 (18% identical), and 29 more.
Diseases named in the same sentence as KIFC2 in open-access papers:
KIFC2 is named in the same sentence as 12 diseases in open-access papers, as found by Europe PMC text mining. Sharing a sentence is not in itself a finding about the gene and the disease. The quoted sentences say what the papers report.
prostate carcinoma (5 papers, 2022 to 2025). A carcinoma that arises from epithelial cells of the prostate gland. "Recently, 2 bioinformatic analyses indicate that KIFC2 is a potential prognostic biomarker for colon adenocarcinoma and prostate cancer." (PMID 40299549, 2025). "Recent studies have shown that KIFC2 promotes prostate cancer progression and chemotherapy resistance by mediating NF-κB p65 expression and nuclear translocation." (PMID 40956849, 2025). "KIFC2 promotes prostate cancer progression by regulating p65." (PMID 38566813, 2024). "Interestingly, it was recently documented that KIFC2 promotes progression and chemoresistance in prostate cancer by activating the NF-κB signaling pathway and is a potential prognostic biomarker in colon and prostate cancers." (PMID 40299549, 2025). "Based on the HPA database, it was found that the expression of KIFC2 was low in prostate and prostate cancer tissue with no mention of CRPC, as well as low and medium expression in a variety of normal tissues and cancer types." (PMID 35620461, 2022). "However, kinesin family member C2 (KIFC2), one of the kinesin-14 motor family members, remains largely unknown in prostate cancer (PCa) progression." (PMID 37716704, 2023).
breast carcinoma (3 papers, 2020 to 2025). "KIFC2-overexpressing cells exhibited increased sensitivity to the antimetabolite chemotherapy agent capecitabine, which is effective for the clinical treatment of breast cancer." (PMID 40299549, 2025). "The hypomethylated probe cg04794268, located in the promoter of KIFC2, widely mediated the associations between almost all micronutrients and breast cancer in our study, although no report about the relationship between KIFC2 and breast cancer has been found so far." (PMID 37630812, 2023).
colon cancer (2 papers, 2023 to 2025). "Nonetheless, the association of KIFC2 expression levels with the prognosis of patients with colon cancer remains unclear." (PMID 37904433, 2023). "Subsequently, in the GEPIA2 database, the expression level of KIFC2 in rectal cancer (READ) was significantly lower than that of the control group, while the expression level of KIFC3 in colon cancer (COAD) was significantly higher than that of the control group (p < 0.05)." (PMID 40299423, 2025).
asthma (1 paper, 2024). "Additional genetic factors, such as genetic variations in some PCD-causing genes (DNAH14, DNAAF3, DNAH6, DNAH5, KIFC2, KIF3A), are associated with the increased risk of asthma development." (PMID 39337527, 2024). "One study has shown that the expression of PCD-related genes, DNAH5, KIFC2 and KIF3A, are downregulated in asthma, and that SNPs in these genes correlate with asthma and disease severity." (PMID 39337527, 2024).
neuroblastoma (1 paper, 2025). Neuroblastoma (NB) is the most common solid, extracranial childhood tumor. "Analogous to KIFC2, the proto-oncogene MYCN is amplified and promotes pyrimidine nucleotide biosynthesis in neuroblastoma cells." (PMID 40299549, 2025).
rectum adenocarcinoma (1 paper, 2023). An adenocarcinoma arising from the rectum. "Compared with corresponding normal tissue, KIFC2 showed significantly higher (P < .05) expression levels in COAD, rectum adenocarcinoma and other cancer types." (PMID 37904433, 2023).
tumor (6 papers, 2022 to 2025). "In clinical settings, it was also found that high KIFC2 mRNA expression was associated with tumor growth and poor survival of patients with HR+/HER2– BC who received ET alone or in combination with CDK4/6 inhibitors." (PMID 40299549, 2025). "In vivo assays using xenograft tumor models in mice further demonstrated that reduced tumor growth and enhanced sensitivity to Tam and Abema caused by silencing of KIFC2 were partially reversed by CDK4 overexpression." (PMID 40299549, 2025). "During multivariate analysis involving age, gender, and tumor stage, high expression of KIFC2 was also significantly associated with a worse prognosis of COAD (HR = 1.8, P = .018)." (PMID 37904433, 2023). "As expected, mRNA levels of KIFC2 were markedly elevated in tumor compared with normal control tissues in both the FUSCC and TCGA data sets." (PMID 40299549, 2025). "Fourth, KIFC2 exerted its tumor-promoting and therapy-resistant functions in HR+/HER2– BC by recruiting USP9X to stabilize CDK4." (PMID 40299549, 2025). "Next, we assessed the effects of KIFC2 on the tumorigenic ability of HR+/HER2– BC cells in xenograft tumor models in mice." (PMID 40299549, 2025). "KIFC2 is crucial for tumor development and drug resistance and has been identified as a potential biomarker or therapeutic target for cancer treatment." (PMID 39131609, 2024). "To confirm that KIFC2 induces tumor progression and Enza resistance dependent on NF-κB p65, we detected the effect of Enza on the proliferation of KIFC2-overexpressing PCa cells pretreated with NF-κB chemical inhibitors GSK583." (PMID 37716704, 2023). "When considering other factors related to COAD such as age, gender, tumor location, stage and MSI status, high expression of KIFC2 remained an independent risk factor for worse prognosis during multivariate analysis (HR = 1.7, P = .028)." (PMID 37904433, 2023). "In vivo studies showed that KIFC2-overexpression mice experienced significant increase in tumor volumes and weights than control groups, while GSK583 treatment partially reversed this promoting effect." (PMID 37716704, 2023). "Additionally, mRNA levels of KIFC2 were positively correlated with expression levels of Ki-67 as determined by IHC staining and with tumor size in patients with HR+/HER2– BC in the FUSCC data set." (PMID 40299549, 2025). "However, there is a need for further investigation to elucidate the mechanisms by which KIFC2 affects ferroptosis in various tumor types." (PMID 39131609, 2024). "Also, the immunohistochemical staining of tumor tissues also confirmed the elevated expression of KIFC2 in PCa with higher Gleason scores." (PMID 37716704, 2023). "Next, whether the KIFC2 expression impact on tumor microenvironment was explored." (PMID 37904433, 2023). "We next assessed protein expression levels of KIFC2, USP9X, and CDK4 in 45 tumor samples from patients with HR+/HER2– BC by IHC." (PMID 40299549, 2025). "With the exception of ASMTL, we observed upregulated mRNA levels of KIFC2, SMYD2, TFRC, and OPN3 in tumor tissues within these datasets." (PMID 39131609, 2024). "The tumor mutation burden levels and microsatellite instability (MSI) status between COAD patients with high and low KIFC2 expression levels were also comparable (P > .05, data not shown)." (PMID 37904433, 2023). "So far, no report about the relationship between KIFC2 and tumor progression has been found." (PMID 35620461, 2022).
cancer (5 papers, 2022 to 2025). A tumor composed of atypical neoplastic, often pleomorphic cells that invade other tissues. "Although dysregulation of KIFs has been linked to human cancers and certain KIFs are currently being validated as anticancer drug targets, information on the structure and function of KIFC2 remains relatively limited." (PMID 40299549, 2025). "As the functional roles of KIF14 in human cancer including BC have been documented previously, we chose the poorly characterized KIFC2 as the focus of this study." (PMID 40299549, 2025). "To determine the regulatory mechanism by which KIFC2 promotes cancer progression and chemoresistance in PCa, we performed functional analysis of differentially expressed genes associated with KIFC2 based on TCGA database." (PMID 37716704, 2023). "Our bioinformatics analysis of the cancer genome atlas and GEO databases revealed significantly higher expression of KIFC2 in COAD, correlating with a worse prognosis in the cancer genome atlas-COAD and GSE17536 cohorts." (PMID 37904433, 2023). "The role of KIFC2 underlying CRC and other cancer types remains undefined." (PMID 37904433, 2023). "In the TCGA dataset, expression levels of KIFC2 varied among different cancer types." (PMID 37904433, 2023).
infection (1 paper, 2025). The state of being infected such as from the introduction of a foreign agent such as serum, vaccine, antigenic substance or organism. "To determine the biological functions of KIFC2 in HR+/HER2– BC, we stably overexpressed Flag-KIFC2 or depleted endogenous KIFC2 in HR+/HER2– MCF7 and T47D cells by lentiviral infection." (PMID 40299549, 2025).
KIFC2 also shares sentences with these, for which no sentence is quoted: colon adenocarcinoma (1 paper); glioma (1); rectal cancer (1).